LRRC15 (leucine rich repeat containing 15)
Diseases named in the same sentence as LRRC15 in open-access papers (continued):
Sharing a sentence is not in itself a finding about the gene and the disease.
tumor (60 papers, 2007 to 2025). "LRRC15+ CAFs have been associated with tumor promotion, immunotherapy resistance, and inhibition of CD8+ T cell function." (PMID 41008788, 2025). "In pancreatic ductal adenocarcinoma (PDAC), PLXDC1+ tumor-associated pancreatic stellate cells (TPSCs) are located adjacent to LRRC15+ myCAFs and SPP1+ macrophages, collectively forming a desmoplastic and immunosuppressive perimeter that promotes CD8+ TEX." (PMID 41425545, 2025). "Col11a1+ CAFs, which co-express LRRC15, are also associated with tumour progression in scRNA-seq and tissue-staining studies." (PMID 38791926, 2024). "A clinical trial involving more than 600 patients with different tumor types showed that elevated levels of LRRC15+ myCAFs signaling were associated with poor outcomes after anti-PD1 therapy." (PMID 38540204, 2024). "Mac Mrc1-enriched spots were enriched at the tumour periphery, and correlation analysis revealed a significant positive association between Mac Mrc1 and Meg3, Fbln1 and Lrrc15 CAF subtypes, which suggested proximity." (PMID 37605008, 2023). "Tumours from DT-treated DTR– mice had a predominant population of LRRC15+ CAFs, whereas DT treatment in DTR+ tumours resulted in an approximately 98% loss of total LRRC15+ cells." (PMID 36171287, 2022). "This population was also observed in human tumours, with clinical trial data showing that the LRRC15+ CAF signature was associated with poor response to immunotherapy, suggesting an immunosuppressive role for these cells." (PMID 34638468, 2021). "Tumor growth inhibition was associated with a dramatic reduction in the number of LRRC15-expressing tumor cells." (PMID 32210091, 2020). "A higher abundance of these normal‐like CAFs in relation to LRRC15+ myCAFs has been associated with immunocompetent tumors, supporting further that they may be major players in restraining tumor progression." (PMID 40908670, 2025). "Elevated LRRC15 expression was associated with a higher tumor grade and poorer prognosis." (PMID 40940809, 2025). "Moreover, two novel ADCs were designed to target stroma components: tumor-associated fibroblast antigens LRRC15 and FAP (fibroblast activation protein α)." (PMID 34206707, 2021). "Wnt signalling, which we identified as downregulated, is required for fibroblast activation, and LRRC15, a marker for activated, myofibroblast-like CAFs, was also notably downregulated in KO tumours." (PMID 41226720, 2025). "ABBV-085, a monomethyl auristatin-E (MMAE) antibody–drug conjugate targeting LRRC15, demonstrated anti-tumour efficacy in preclinical models." (PMID 39780187, 2025). "The tumour-promoting characteristic of CAFs with high LRRC15 expression has inspired the development of LRRC15-targeted therapies." (PMID 39780187, 2025). "Payload-delivery strategies (e.g., antibody–drug conjugates to LRRC15/FAP) can leverage stromal–tumor co-expression but require the demonstration of tumor-dominant expression to mitigate off-tumor toxicity." (PMID 40940809, 2025). "To address the challenge of target heterogeneity that limits the efficacy of classical antibody-drug conjugates, we deployed this novel platform to harness the radiation deposited in LRRC15+ cells to eliminate adjacent LRRC15-null tumor tissue." (PMID 41022704, 2025). "Where target antigens are co-expressed by the stroma and tumor (e.g., LRRC15, FAP), prefer payload-delivery strategies if the expression is tumor-dominant, and avoid indiscriminate stromal depletion when the lineage is ambiguous." (PMID 40940809, 2025). "Selective depletion of LRRC15 + CAFs has shown promise in slowing tumor growth, reducing metastasis, and enhancing the efficacy of immunotherapy." (PMID 41008788, 2025). "Imaging by SPECT at 72 h post-[177Lu]Lu-DUNP19 administration revealed LRRC15-specific accumulation of activity at the tumor site." (PMID 41022704, 2025).
tumor (continued). "According to tumor histology, LRRC15 is highly expressed in mixed tumors compared to infiltrating ductal, infiltrating lobular, mucinous, medullary, and metaplastic tumors." (PMID 38611080, 2024). "Collectively, these findings demonstrate that TGFB1-dependent LRRC15-positive CAFs dictate the tumor-fibroblast setpoint to promote tumor growth." (PMID 38892190, 2024). "Regarding BC molecular subtypes, LRRC15 showed a high expression in all molecular subtypes compared to non-tumor samples." (PMID 38611080, 2024). "Ablation of LRRC15+ CAFs in mouse models was also able to enhance anti-tumour immunity and ICB response." (PMID 38791926, 2024). "Comparing the tumor samples with metastatic ones, we observed significant results for LRRC15, TSPAN13, and CA12 as determined by Dunn’s test (p < 0.05)." (PMID 38611080, 2024). "For example, sc-RNAseq showed that several clusters of LRRC15+ myofibroblasts which promote tumor growth also highly expressed aSMA31." (PMID 37898598, 2023). "More importantly, a recent scRNA-seq analysis of fibroblasts from normal pancreas and PDAC provided insights into fibroblast evolution during tumor progression, identifying LRRC15+ CAFs of prognostic significance in immunotherapy clinical trials." (PMID 37784082, 2023). "According to these findings, the study instead noted a tumor-supporting role for LRRC15+ myoCAFs in PDAC." (PMID 37771596, 2023). "In contrast, multiple genes were upregulated in tumour-associated myofibroblasts compared to their control counterparts, including SULF1, COL11A1 and LRRC15." (PMID 36720863, 2023). "diphtheria toxin (DT) can selectively deplete the pro-tumor CAFs subtype LRRC15+CAFs, and can also lead to CAFs components being recalibrated towards universal fibroblasts." (PMID 37666813, 2023). "A previous study found that compared with matched primary tumours, LRRC15 was highly expressed in intestinal OC metastasis samples and was an active promoter of omentum metastasis." (PMID 36653841, 2023). "LRRC15+ CAFs suppress tumor immunity, reduces the response to immunotherapy, and drives tumor growth." (PMID 38002057, 2023). "We found that only LRRC15 was still highly expressed in tumour tissues (including stroma and parenchyma), and the differences were statistically significant." (PMID 36653841, 2023). "Further statistical analysis showed that the expression of LRRC15 was correlated with tumour stage and primary treatment outcome." (PMID 36653841, 2023). "Using newly developed Lrrc15–diphtheria toxin receptor knock-in mice to selectively deplete LRRC15+ CAFs, we show that depletion of this population markedly reduces the total tumour fibroblast content." (PMID 36171287, 2022). "As a result, tumour growth was significantly slowed following sustained depletion of LRRC15+ CAFs in DTR+ mice compared with DTR– control mice." (PMID 36171287, 2022). "Despite the significant reduction in LRRC15+ cells in Dptki/kiTgfbr2fl/fl tumours, the total number of PDPN+CD31– fibroblasts was unchanged between both groups, which indicated that a compensation mechanism occurred to maintain the CAF compartment." (PMID 36171287, 2022). "We aimed to provide an in vivo genetic link between these two inferences, proposing that TGFβ signalling in universal fibroblasts is indispensable for the formation of LRRC15+ myofibroblasts during tumour progression." (PMID 36171287, 2022). "Mice in which LRRC15+ CAFs were depleted exhibited significantly reduced tumour burden compared with mice with sufficient LRRC15+ CAFs." (PMID 36171287, 2022). "As expected, LRRC15+ cells were found surrounding tumour islets (in keeping with their myCAF phenotype), however they were also frequently seen in proximity to CD8+ T-cells." (PMID 36358721, 2022). "Within KPR tumours, LRRC15 expression was restricted to PDPN+ fibroblasts and largely absent in other compartments." (PMID 36171287, 2022).
tumor (continued). "Collectively, these data show that selective ablation of the LRRC15+ subtype of CAFs in tumours leads to a significant decrease in total CAF content and a marked and persistent reduction in tumour burden." (PMID 36171287, 2022). "Together, these data indicate that depletion of LRRC15+ CAFs not only reduces overall fibroblast content in KPR tumours but also recalibrates the setpoint of the remaining CAFs towards a more universal fibroblast-like state." (PMID 36171287, 2022). "The LRRC15+ CAF signature correlates with poor response to immune-checkpoint blockade in several different human tumor types." (PMID 36293532, 2022). "Immunofluorescence analysis of KPR tumours revealed a significant proportion of tumour-infiltrating CD8+ T cells in close proximity with LRRC15+ CAFs, which suggested that direct cell-to-cell interactions were occurring." (PMID 36171287, 2022). "As a result, Dptki/kiTgfbr2fl/fl tumours had a significant reduction in the total number of LRRC15+PDPN+ CAFs compared with control Dptwt/wtTgfbr2fl/fl tumours, which indicatedthat LRRC15+ cells depend on TGFβR2 signalling in DPT+ cells for their formation." (PMID 36171287, 2022). "LRRC15+ and LRRC15– CAFs from DTR– tumours or PDPN+ LRRC15-depleted CAFs from DTR+ tumours were sorted 12 days after DT treatment." (PMID 36171287, 2022). "LRRC15 belongs to the leucine-rich repeat superfamily, and numerous studies have shown that LRRC15 is induced and highly expressed in various tumor types." (PMID 36317112, 2022). "Given the specificity of Lrrc15 expression, we proceeded to assess the impact of selectively depleting LRRC15+ CAFs on tumour growth." (PMID 36171287, 2022). "Collectively, these findings demonstrate that TGFβ-dependent LRRC15+ CAFs dictate the tumour-fibroblast setpoint to promote tumour growth." (PMID 36171287, 2022). "ABBV-085 is a monomethyl auristatin E (MMAE)-containing antibody-drug conjugate (ADC) designed to target LRRC15, and which has shown significant anti-tumor activity in several tumor models." (PMID 32210091, 2020). "LRRC15 has been shown to be highly expressed on CAFs within the tumor stroma of many epithelial tumors." (PMID 32210091, 2020). "With tumor progression, they specifically observed an increase in the frequency of CAFs programmed by TGF-β and expressing the leucine-rich repeat containing 15 (LRRC15) protein encoding a conserved transmembrane protein." (PMID 32752017, 2020). "PI15 (peptidase inhibitor 15) was downregulated, whereas LRRC15 (leucine rich repeat containing 15) was upregulated in both tumor cells." (PMID 17389037, 2007). "Notably, the specific depletion of LRRC15+ cells through a single systemic administration of [177Lu]Lu-DUNP19 significantly slowed tumor progression and conferred a survival benefit in all models." (PMID 41022704, 2025). "It further identifies PLXDC1+ PSCs near aggressive LRRC15+ cancer‐associated myofibroblasts and SPP1+ macrophages, forming a desmoplastic and immunosuppressive tumor niche that promotes CD8+ T cell exhaustion, contributing to poor immunotherapy outcomes in pancreatic cancer." (PMID 40091495, 2025). "The elevated levels of LRRC15-positive CAFs signatures correlated with poor responses to anti-PD-L1 therapy, and the depletion of LRRC15-positive CAFs markedly reduced the total tumor fibroblast content, which relieves the direct suppression of CTLs and augments tumor regression." (PMID 38892190, 2024). "LRRC15-expressed fibroblasts surround tumor islets, and its expression was induced by TGFB1 (SE = 6.0); hence, it could be a marker of myCAFs rather than iCAFs." (PMID 38892190, 2024). "PTK7, SERPINH1, and FAP could discriminate PanIN versus tumor‐related stroma by contrast to αSMA and LRRC15." (PMID 36587397, 2023). "Furthermore, the anti-LRRC15 antibody ABBV-085 has shown efficacious in tumor regression, and then the combination therapy expanded the therapeutic benefits." (PMID 37784082, 2023).
tumor (continued). "Moreover, LRRC15+ myoCAF depletion in combination with anti-PDL1 led to a significantly improved anti-tumor effect." (PMID 37771596, 2023). "In tumour tissue, on day 0, Pi16+ cells and Lrrc15+ cells were detected." (PMID 36171287, 2022). "Eight days later, tumours were collected and evaluated for the presence of LRRC15+ CAFs." (PMID 36171287, 2022). "First, we determined whether the improved tumour control observed following LRRC15+ CAF ablation depends on CD8+ T cells." (PMID 36171287, 2022). "Also missing is in vivo substantiation of the cellular and molecular signals that promote LRRC15+ myofibroblast development and their direct impact on anti-tumour immunity." (PMID 36171287, 2022). "Additionally, we utilized the transwell assay and carboxy fluorescein succinimidyl ester (CFSE) tracking to further confirm the effects of LRRC15 on attracting microglia/macrophages and tumour cell proliferation in the TME." (PMID 33960636, 2021). "Despite the obvious efficacy of ABBV-085 to reduce tumor growth in tumors with high expression of LRRC15, we could observe, in some STS PDX models, a similar activity with the non-binding control (hIgG-MMAE)." (PMID 32210091, 2020). "Recent work has shown that the molecule leucine-rich repeat-containing protein 15 (LRRC15 or hLib), frequently overexpressed in tumor cells, could result in the redistribution of CAR away from cell surfaces, thus impeding Ad infection." (PMID 20543907, 2010). "Also the TGFβ-driven expression of the leucine-rich-repeat-containing protein 15 (LRRC15) in CAFs, characterizes a pro-tumorigenic CAF subpopulation, as the depletion of LRRC15+ CAFs in PDAC models slowed tumor growth and restored CD8+ T cell functions, increasing response to immunotherapy." (PMID 36324182, 2022). "Together with the results from our genetic mouse system, these findings suggest that TGFβ signalling acts a rheostat to dictate the tumour fibroblast setpoint between universal fibroblasts and LRRC15+ myofibroblasts and may serve as a potential predictor of patient outcome." (PMID 36171287, 2022). "It remains unclear whether LRRC15+ CAFs underlie this lack of response or whether they represent a readout of tumour-intrinsic features that drive the association." (PMID 36171287, 2022). "We show, at a transcriptomic level, that these TGFβ-LRRC15 signatures are largely erased in [177Lu]Lu-DUNP19-treated tumors and expression of other anti-tumor immune pathways increases." (PMID 41022704, 2025). "RKO tumor FFPE sections were stained with antibodies against FAP and LRRC15, along with HA-binding protein (HABP) to confirm the high levels of FAP and LRRC15 proteins in the tumor samples with a concomitant abundance of HA within the TME." (PMID 41228205, 2025). "FAP has been favored by its more restricted expression patterns within the tumor stroma compared to α‐SMA, whereas LRRC15 has been more recently reported in scRNAseq analyses and associated with strong immunosuppression." (PMID 40908670, 2025). "Our analysis consistently confirmed the increased expressions of LRRC15, EFNA3 TSPAN13, and CA12 in tumor samples, consistent with TCGA data findings from the DS and VS cohorts." (PMID 38611080, 2024). "As a result, we identified four membrane proteins—LRRC15, EFNA3, TSPAN13, and CA12—that demonstrated high expressions in BC tissues compared to adjacent non-tumor breast tissues and other healthy samples, with a few exceptions." (PMID 38611080, 2024). "Our analysis revealed that LRRC15 and CA12 exhibited increased expressions in BC samples compared to non-tumor samples." (PMID 38611080, 2024). "Several molecular processes are involved in this mechanism of tumor cell resistance, namely Ras-related protein Rab-25 (RAB25) small GTPase, integrin members, and leucine rich repeat containing 15 (LRRC15)." (PMID 38068912, 2023).
tumor (continued). "The expression differences of LRRC15 and LRRC32 in HGSC tumour tissues and normal ovarian epithelial tissues were visualized by the GGplot2 package in R software." (PMID 36653841, 2023). "LRRC15+CAF have been found to hamper the function of CD8+ T cells, and specific consumption of LRRC15+CAF using Lrrc15-diphtheria toxin receptor inhibited tumor growth and increased ICB response." (PMID 37784082, 2023). "LRRC15+ CAF-sufficient mice showed some sensitivity to anti-PDL1 treatment, as demonstrated by a partial reduction in tumour burden." (PMID 36171287, 2022). "Conversely, responsiveness to anti-PDL1 treatment was significantly potentiated in LRRC15+ CAF-depleted mice, as reflected in the more substantial reduction in tumour burden." (PMID 36171287, 2022). "Always using transgenic mice models, Krishnamurty and colleagues selectively depleted the LRRC15+ CAF subpopulation in PDAC, and this was sufficient to significantly slow tumor growth and restore CD8+ T cell functions, increasing response to immunotherapy." (PMID 36324182, 2022). "We hypothesize that the high EFFscore subgroup may secrete ANGPTL4 and MDK to activate myCAF populations, particularly LRRC15+ Fib and STRA6+ Fib, thereby driving late-stage ECM remodeling and promoting tumor invasion and metastasis." (PMID 41383622, 2025). "Notably, PLXDC1+ TPSCs, located near aggressive LRRC15+ myCAFs and SPP1+ macrophages, formed a desmoplastic and immunosuppressive niche around the tumor boundary, promoting CD8 T cell exhaustion." (PMID 40091495, 2025). "LRRC15+ CAFs also promote tumor growth and suppress CD8+ T cell function, indicating that therapies targeting LRRC15 may enhance patient survival and responses to immunotherapy." (PMID 41228205, 2025). "Recently, a study demonstrated that leucine rich repeat containing 15 (LRRC15) displayed a more specific expression pattern in myCAFs, and targeted depletion of LRRC15+ myCAFs resulted in a substantial 70% reduction in overall PDPN+ CAFs, significantly attenuating PDAC tumour growth." (PMID 39780187, 2025). "Critically, we have demonstrated that [177Lu]Lu-DUNP19 therapy can be effective despite heterogenous LRRC15 expression within tumor tissue, and in contexts where the tumor cells themselves do not express the target." (PMID 41022704, 2025). "Despite LRRC15 expression in stroma only, a single systemic injection of 20 MBq [177Lu]Lu-DUNP19 effectively suppressed HCC1954 tumor growth and significantly prolonged median survival compared to untreated mice (p = 0.0001; median survival not reached vs. 30.5 days)." (PMID 41022704, 2025). "Interestingly, both LRRC15 and EFNA3 showed significant overexpressions in all subtypes, including TNBC, when compared to non-tumor breast tissue." (PMID 38611080, 2024). "A subset of CAFs in PDAC mouse models also express LRRC15, which was not expressed in normal pancreas and was postulated to promote tumor growth and inhibit anti-tumor immune responses." (PMID 38398185, 2024). "Immunofluorescence imaging confirmed these results, showing an absence of LRRC15 staining in DTR+ tumours." (PMID 36171287, 2022). "Maintenance of the total fibroblast content in the absence of LRRC15+ CAF formation in Dptki/kiTgfbr2fl/fl tumours warranted a deeper investigation of the fibroblast composition in these mice." (PMID 36171287, 2022). "Outside tumours, in situ hybridization and bulk RNA-seq12 analysis showed that Lrrc15 expression was low to absent across multiple tissues." (PMID 36171287, 2022). "Depletion of CD8 T cells reversed this effect, which indicated that CD8+ T cells have a role in reducing tumour burden in the absence of LRRC15+ CAFs." (PMID 36171287, 2022). "Leucine-rich repeat containing 15 (LRRC15) has also been identified as a marker of myCAF-like cells in mouse PDAC, and TGFβ-driven LRRC15+ cells have been shown to dominate the CAF compartment in late-stage tumours." (PMID 36358721, 2022).